TLR3 (toll like receptor 3)
Diseases named in the same sentence as TLR3 in open-access papers (continued):
Sharing a sentence is not in itself a finding about the gene and the disease.
glioblastoma (6 papers, 2009 to 2025). The most malignant astrocytic tumor (WHO grade IV). "For example, TLR3 mRNA molecule is alternatively spliced to produce a smaller 60 kDa isoform, which has been observed to be overexpressed in Glioblastoma cell lines." (PMID 26660865, 2015). "The results suggested that the TLR3 expression levels in glioblastoma multiforme (GBM), LGG, KIRC, PAAD and STAD were significantly elevated compared with those in adjacent nontumor tissues, but the expression levels of TLR3 in testicular germ cell tumors (TGCT) were significantly decreased." (PMID 36419829, 2022). "Synthetic siRNA duplexes have now been show to activate PKR in glioblastoma cells, RIG-I in glioblastoma cells and primary human monocytes, TLR3 in HEK293 cells and murine models, TLR7 in murine leukocytes and human plasmacytoid dendritic cells, and TLR8 in human monocytes." (PMID 19630977, 2009).
Hashimoto thyroiditis (6 papers, 2012 to 2023). An autoimmune disorder caused by the production of autoantibodies against thyroid tissue. "Future research could be directed to investigate whether TLR gene polymorphisms could reduce TLR3 expression levels or alter the functions of TLRs, thus bringing new targeted therapies for patients with Hashimoto’s thyroiditis." (PMID 33981318, 2021). "TLR3 is highly expressed in the thyrocytes of Hashimoto’s disease patients and may affect the innate immune response." (PMID 37324262, 2023). "Haria’s team in 2005 showed that TLR3 is highly expressed in the thyrocytes of patients with Hashimoto’s disease, which, according to the researchers, may affect the mechanisms of the innate immune response in these cells." (PMID 36982416, 2023). "Furthermore, immunohistochemical studies have shown that TLR3 protein is overexpressed in thyroid cells in patients with Hashimoto’s thyroiditis, but not in thyroid cells in the normal population." (PMID 33981318, 2021).
Hepatitis B infection (6 papers, 2015 to 2025). "Association of TLR3 SNP 1337CT genotypes with symptomatic and asymptomatic status in chronic active and chronic inactive Hepatitis B patients." (PMID 40299876, 2025). "Correlation between HBeAg status and TLR3 SNP 1337CT genotypes in patients with chronic active and chronic inactive Hepatitis B." (PMID 40299876, 2025).
liver diseases (6 papers, 2010 to 2023). "Many liver diseases involve activation of Toll-like receptor 3 (TLR3), which is activated by double-stranded RNA (dsRNA)." (PMID 36654880, 2023). "TLR3 is considered to have a major role in liver diseases and is required for recognizing double-stranded RNA from virus genomes or replication intermediates within infected cells." (PMID 36654880, 2023). "To date, there are a huge number of clinical studies on the association between single nucleotide polymorphisms (SNPs) of TLR3/7 genes and HCV-induced liver diseases, of which studies on TLR3 rs3775290 SNP and TLR7 rs179008 SNP occupy a large proportion." (PMID 37869679, 2023). "In conclusion, we showed that distinct TLR3 polymorphisms were associated with susceptibility to HCV infection and to HCV-related end-stage liver disease progression." (PMID 28127569, 2017). "In this present study, we showed that three other TLR3 SNPs (rs5743313, rs5743314, and rs111611328) were strongly associated with HCV-related end-stage liver disease progression (liver cirrhosis and HCC)." (PMID 28127569, 2017). "In summary, these results indicate that distinct genetic variants of TLR3 SNPs are associated with HCV infection and HCV-mediated liver disease progression in the Saudi Arabian population." (PMID 28127569, 2017). "To investigate whether LIGHT is involved in TLR3-triggered liver diseases, we employed a mouse acute hepatitis model induced by poly(I:C)." (PMID 36654880, 2023). "Growing evidences suggest that TLR3 plays an important role in the pathogenesis of liver diseases." (PMID 36654880, 2023). "In conclusion, our results uncovered a role of LIGHT in poly(I:C)-induced acute hepatitis, which may lead to new therapeutic strategies targeting this molecule in treating liver diseases and shed new insights into the pathogenesis for TLR3-triggered inflammation diseases." (PMID 36654880, 2023). "However, the cellular and molecular mechanisms of TLR3 signaling in liver diseases remain elusive." (PMID 36654880, 2023). "However, the involvement of LIGHT in TLR3 implicated liver diseases is not clear." (PMID 36654880, 2023). "A better understanding of these distinguishable structural and functional features will be helpful for developing therapeutic applications against TLR3-mediated HCV infections and TLR3-mediated, HCV-related liver diseases." (PMID 28127569, 2017). "TLR3, a sensor of the host immune system activated by viral dsRNA and responsible for the production of IFN, has been demonstrated to play an essential role during HCV infection and clearance, as well as in the severity of liver diseases." (PMID 28127569, 2017). "TLR3 polymorphisms (rs1879026 and rs3775290) have been described to be associated with a risk for HBV-related liver diseases in a Chinese population, whereas the same nine SNPs of our study were not correlated with any susceptibility to HBV-related liver diseases in the Saudi Arabian population." (PMID 28127569, 2017).
lymphoma (6 papers, 2017 to 2023). A malignant (clonal) proliferation of B- lymphocytes or T- lymphocytes which involves the lymph nodes, bone marrow and/or extranodal sites. "The mechanisms underlying TLR3-mediated apoptosis may contribute to the development of new drug to treat lymphomas and oncovirus infections." (PMID 28790362, 2017). "Higher levels of TLR3 and TLR5 were associated with a cluster of six sensitive and two resistant lymphomas." (PMID 34913612, 2022). "In this study, we investigated the effects of poly (I:C) on Marek’s disease lymphoma-derived chicken cell line and explored the TLR3-dependent signaling pathways that drive apoptosis in lymphomas cells." (PMID 28790362, 2017). "A recent study developed a strategy called an in situ vaccine, which combined Flt3L, radiotherapy, and a TLR3 agonist (Flt3L for DC expansion, radiotherapy for loading DCs with the antigen, and TLR3 agonist for DC activation) to test its efficacy in a murine lymphoma model." (PMID 36238278, 2022). "One recent study on lymphoma using irreversible electroporation combined with anti-PD1 and TLR3/9 agonists indicated a sound treatment response by reversing the immunosuppressive TME, including the reduction in MDSCs." (PMID 36911674, 2023). "However it is unclear whether TLR3 has same function against chicken lymphoma." (PMID 28790362, 2017). "TLR3 and TLR9 agonists reduce MDSCs in an EG7 lymphoma mouse model." (PMID 36911674, 2023). "For example, the avian leukosis virus (ALV) lymphoma-derived chicken cell line DT40 was tested, and no simple correlation was apparent between TLR3 expression in the resting state and poly (I:C)-induced apoptosis." (PMID 28790362, 2017).
malaria (6 papers, 2009 to 2022). Malaria is a serious and sometimes fatal disease caused by a parasite that commonly infects a certain type of mosquito which feeds on humans. "In contrast, a higher concentration of IP-10 following TLR3 or TLR9 stimulation was associated with a lower hazard of malaria." (PMID 30454004, 2018). "However, the clinical relevance of TLR-mediated immune responses in the susceptibility to malaria has been mainly reported for endosomal PRRs such as TLR3, TLR7/8, and TLR9 in African children." (PMID 30384846, 2018). "Here, we found that Th1 cytokines and chemokines (IL-12 TLR7/8 ratio and IP-10 TLR3 crude) and cytokines induced upon inflammation (IL-1RA TLR7/8 ratio) were associated with a decreased risk of clinical malaria during the first year of life." (PMID 30384846, 2018). "In contrast, an increase in the concentration of IP-10 in TLR3 and TLR9 stimulations was associated with a decreased risk of clinical malaria occurrence in early infancy." (PMID 30384846, 2018). "In addition, certain biomarkers, which levels were significantly modified depending on the PME category, were independent predictors of either malaria risk (GM-CSF TLR7/8 crude) or protection (IL-12 TLR7/8 ratio and IP-10 TLR3 crude, IL-1RA TLR7/8 ratio) during the first year of life." (PMID 30384846, 2018). "Stimulation with polyinosinic-polycytidylic acid (TLR3), LPS (TLR4), and/or CpG oligonucleotide type A (TLR9) has been associated with altered cytokine production in whole cord blood or cord blood mononuclear cells isolated from infants born to mothers exposed to malaria in pregnancy." (PMID 30454004, 2018). "To gain further insights into the potential of RIG-I/MDA5 and TLR3 ligands to induce protective immune responses against malaria, we tested the adjuvant effects of a RIG-I agonist, 5’-triphosphate double-stranded RNA (5’ppp-dsRNA), and a TLR3 agonist, polyadenylic–polyuridylic acid or poly(A:U)." (PMID 35669785, 2022).
myocardial infarction (6 papers, 2018 to 2025). Gross necrosis of the myocardium, as a result of interruption of the blood supply to the area, as in coronary thrombosis. "In another example, myocardial infarction was found to be attenuated in TLR3-deficient mice as a result of the activation of the TLR3-TRIF pathway by extracellular RNA (exRNA) released from damaged tissue, although the authors did not define the source and identity of the RNA." (PMID 33392206, 2020). "The main TLRs expressed in myocardial cells include TLR2, TLR3, and TLR410, wherein TLR4 is involved in myocardial injury caused by myocardial infarction." (PMID 38159178, 2024). "This research sought to investigate the clinical significance of level changes of TLR2, TLR3, TLR4, TNF-α, sTNFR-1, sTNFR-2, EPCs, and VEGF in elderly patients with recurrent myocardial infarction after coronary stent implantation." (PMID 35425840, 2022). "Levels of TLR2, TLR3, TLR4, TNF-α, sTNFR-1, and sTNFR-2 were remarkably increased (P < 0.001), and EPCs and VEGF were remarkably lowered (P < 0.001) in the elderly patients with recurrent myocardial infarction after coronary stent implantation." (PMID 35425840, 2022). "Expressions of TLR2, TLR3, and TLR4 were demonstrated in atherosclerotic lesions and led to the development of the atherosclerotic lesions, atherosclerotic arterial occlusion, and acute myocardial infarction." (PMID 35425840, 2022). "Interestingly, post myocardial infarction TLR and IRF gene expression was almost exclusively increased in the infarct zone after myocardial ischemia (Tlr2, Tlr3, Tlr6, Tlr7, Tlr9, Irf3, Irf7)." (PMID 29538462, 2018). "Many previous reports showed that expressions of TLR2, TLR3, and TLR4 as proatherogenic receptors were related to the extent and severity of coronary heart disease and led to the development of the atherosclerotic lesions, atherosclerotic arterial occlusions, and acute myocardial infarction." (PMID 35425840, 2022).
oral squamous cell carcinoma (6 papers, 2016 to 2026). "In contrast, a worse prognosis was observed with increased TLR3 expression in oral squamous cell carcinoma and prostate cancer." (PMID 39988665, 2025). "Approximately 73.2% of oral squamous cell carcinoma (OSCC) tissues express TLR3, and TLR3 expression is correlated with poorly differentiated tumors." (PMID 33986756, 2021). "The recent description of a crosstalk between TLR3 and HIF-1α in 2 oral squamous cell carcinoma cell lines raises the issue of the potential relationship between TLR3 and metabolic reprogramming in cancer cells." (PMID 27791989, 2016). "Our results confirm that TLR3 and TLR4 are highly expressed in oral squamous cell carcinoma (OSCC)." (PMID 27191981, 2016).
pancreatitis (6 papers, 2009 to 2024). Inflammation of the pancreas. "In this study, we chose a mouse model of pancreatitis induced by taurocholate to evaluate the anti-inflammatory properties of ADSCs activated with a TLR3 agonist poly(I : C), and explored the underlying of enhanced anti-inflammatory mechanism." (PMID 38550755, 2024). "Regarding the protective role of polyI:C in preventing AP, TLR3 agonists are promising therapeutic agents to safely and effectively prevent AP at the early stages of pancreatitis." (PMID 31130960, 2019). "Other Toll-like receptors were also associated with pancreatitis, including TLR3 and TLR6, whose genetic polymorphisms are associated with the occurrence of severe pancreatitis." (PMID 26347203, 2015). "Therefore, this study aims to transform adipose-derived stem cells (ADSCs) into MSC2 phenotype by pretreated with TLR3 agonist poly(I : C), to evaluate the anti-inflammatory properties in a pancreatitis mouse model and to explore the mechanisms of enhanced anti-inflammatory effects." (PMID 38550755, 2024).
pneumococcal pneumonia (6 papers, 2017 to 2024). A febrile disease caused by STREPTOCOCCUS PNEUMONIAE. "In this work, we showed that the CRL1505 strain is capable of increasing the resistance to the secondary pneumococcal pneumonia produced after TLR3 activation or RSV infection through modulation of the gut–lung axis." (PMID 39766307, 2024). "In the end, we studied whether the immunization protocol including the PSPF and the mucosal adjuvants Cp 090104 and BLPs could influence the resistance of the mice to secondary pneumococcal pneumonia produced after the inflammatory lung damage triggered by TLR3 activation." (PMID 38675794, 2024). "Thus, we speculated that nasally administered postimmunobiotics contribute to the generation of trained alveolar macrophages during RSV infection or TLR3 activation, in this way increasing the protection against secondary pneumococcal pneumonia." (PMID 36363777, 2022). "Additionally, whether the immunization protocols, including Cp and CP-derived BLPs, together with the pneumococcal vaccines can enhance the resistance to secondary pneumococcal pneumonia induced after inflammatory lung damage mediated by the activation of Toll-like receptor 3 (TLR3) was assessed." (PMID 38675794, 2024). "NV1505 or PG1505 differentially regulated the respiratory innate antiviral immune response triggered by the activation of Toll-like receptor 3 (TLR3), improving the resistance to a primary RSV infection and secondary pneumococcal pneumonia." (PMID 32660087, 2020). "We demonstrated that the nasal priming with viable C. pseudodiphtheriticum 090104 differentially modulated TLR3-mediated innate antiviral immune response in the respiratory tract of infant mice, improving their resistance to primary RSV infection, and secondary pneumococcal pneumonia." (PMID 28878760, 2017).
preeclampsia (6 papers, 2012 to 2025). Preeclampsia is a hypertensive disorder of pregnancy that is characterized by new-onset hypertension with proteinuria presenting after 20 weeks of gestation, and depending on mild or severe forms may initially present with severe headache, visual disturbances, and hyperreflexia. "The same authors examined TLR3/7/8 activation in placentas from women diagnosed with preeclampsia and found increased mRNA levels of TLR3/7/8 but also elevated proinflammatory cytokine levels." (PMID 23880853, 2013). "The same preeclampsia-symptoms, in addition to excessive inflammation, were shown in pregnant mice, after TLR3/7/8 activation following treatment with polyI:C, R-837, and CLO97 agonists, respectively." (PMID 23880853, 2013). "Interestingly, the most pronounced increase in fold change was observed for the pro-inflammatory cytokines IL-1β, IL-8 and for TLR3, which are key mediators of inflammation in preeclampsia." (PMID 31991780, 2020). "In preeclampsia, placental expression of TLR3, TLR7, and TLR8 are upregulated." (PMID 32260307, 2020). "Furthermore, the expression level of TLR3 is higher in decidua from normal pregnancies compared to preeclampsia, but there is a contrary result in placental trophoblasts, suggesting that TLR3 is involved in local inflammatory regulation at the maternal–fetal interface in humans." (PMID 40218311, 2025).
SARS-CoV infection (6 papers, 2020 to 2022). "TLR3 knockout mice are more susceptible to SARS-CoV infection, and TLR3/7 knockdown impairs SARS-CoV-2 sensing of Calu-3 cells." (PMID 35204803, 2022). "Studies have revealed that TLR3−/−-, TLR4−/−-, and TRIF-related adaptor molecule (TRAM)−/−- deficient mice are more vulnerable to SARS-CoV infection and show greater transient weight loss when compared to wild-type mice." (PMID 35847031, 2022). "As a proof of concept, TLR3/TLR4 double-negative mice were more susceptible to SARS-CoV infection, and the deletion of TRIF increased the SARS-CoV-dependent risk of mortality." (PMID 34576716, 2021). "The production of TLR-3 has been also reported in the SARS-CoV infection which, despite its ability to protect host cells against the virus, might be responsible for lung tissue injury." (PMID 32582303, 2020). "The activation of TLR-3 and TLR-4 through TRIF adapter protein imposes strong cell-intrinsic defense response against SARS-CoV infection." (PMID 33262955, 2020). "Mice lacking TRIF (the adaptor protein for TLR3 and TLR4) are more susceptible to SARS-CoV infection." (PMID 35847031, 2022). "This prompted the usage of TLR-3 and TLR-4 agonists to have protection against SARS-CoV infection." (PMID 33262955, 2020).
triple-negative breast carcinoma (6 papers, 2015 to 2025). An invasive breast carcinoma which is negative for expression of estrogen receptor (ER), progesterone receptor (PR), and human epidermal growth factor receptor 2 (HER2). "Similarly, exosomes modified with α-lactalbumin (α-LA) delivered human neutrophil elastase (ELANE) and the Toll-like receptor 3 (TLR3) agonist Hiltonol, both inducers of immunogenic cell death, to triple-negative breast cancer (TNBC) models." (PMID 39961904, 2025). "High expression of TLR3 in triple-negative breast cancer predicts better prognosis." (PMID 37005579, 2023). "Using FUSCC multiomics datasets on triple- negative breast cancer (TNBC), we compared the mRNA expression of TLR3 in TNBC tissue and the adjacent normal tissue." (PMID 37005579, 2023). "However, we only investigated 78 cases in the expression studies, and we did not study the influence of TLR3 expression on survival rates in patients with triple-negative breast cancer." (PMID 37005579, 2023).
airway hyperresponsiveness (5 papers, 2011 to 2025). "The results revealed that LPS and poly (I: C) elevated Rrs and Ers, implying that activation of both TLR3 and TLR4 causes airway hyperresponsiveness (AHR)." (PMID 39614276, 2024). "Starkhammar and colleagues showed that combined stimulation of TLR3 and TLR4 causes airway hyperresponsiveness which is increased during an ongoing allergic inflammation." (PMID 34394070, 2021). "Notably, TLR3 activation promotes high expression of IL-13 in type 2 innate lymphoid cells (ILC2) and alveolar macrophages, leading to airway hyperresponsiveness and increased mucus production." (PMID 41293166, 2025).